AFP (alpha fetoprotein)
Diseases named in the same sentence as AFP in open-access papers (continued):
Sharing a sentence is not in itself a finding about the gene and the disease.
tumor (continued). "Univariate and multivariate analyses were performed for Child-Pugh grade, BCLC Stage, tumor number, microvascular invasion, AFP, ALB, IINS, and other clinicopathologic variables." (PMID 36016629, 2022). "HCC patients with high- and low-EXO1 expression levels showed significant differences in the clinical T stages, pathological stages, tumor status, histological stages, alpha-fetoprotein (AFP) levels, overall survival (OS), and disease-specific survival (DSS)." (PMID 35769911, 2022). "Recurrence and peritoneal metastasis were judged on the basis of tumor markers such as alpha-fetoprotein (AFP), and imaging data such as computed tomography (CT) and magnetic resonance imaging (MRI)." (PMID 36397082, 2022). "In a recent study considering the effect of listing characteristics including tumor size and number, AFP, CTP, and MELD‐Na score on post‐LT survival, inferior 5‐year post‐LT survival was observed in the highest risk stratum." (PMID 35029055, 2022). "A high Hypoxia_DEGs_Score was found in patients with elevated alpha-fetoprotein, higher tumor stage, worse pathological stage and grade, as well as a higher tumor recurrence rate." (PMID 36059442, 2022). "Alpha-fetoprotein (AFP) (HR =2.360, P = 0.005) and tumor number(HR=2.786, P=0.000) were independent prognostic factors for RFS." (PMID 36212462, 2022). "Patients with an elevated AFP level were more likely to have an advanced T stage as well as poorly differentiated tumours in pathological examination." (PMID 36233670, 2022). "Six preoperative variables, namely tumor number, infiltrative appearance, corona enhancement, alpha-fetoprotein (AFP) level, aspartate aminotransferase (AST) level, and sex, were independently associated with recurrence." (PMID 35554652, 2022). "A new meta-analysis specified that SCCA and SCCA IgM show moderate diagnostic precision as new tumor markers of HCC, though the significance of the integration of SCCA/SCCA IgM and AFP needs further research." (PMID 35547447, 2022). "For patients with HCC with a tumor size of 3–5 cm, tumor number of two to three, or AFP >400 μg/L, it becomes difficult for RFA alone to reach at least 1 cm of safety margin beyond the tumor at every direction." (PMID 35814378, 2022). "CpGf-AFP-sr39 NP treatment resulted in 62% reduced tumor size, and therapeutic gene expression was detectable by positron emission tomography (PET)." (PMID 35857843, 2022). "Further, clinical data showed that upregulation of RPL22L1 in HCC patients was strongly correlated with tumor differentiation, tumor size and serum AFP levels." (PMID 35973992, 2022). "Several typical tumor specific proteins in blood, such as alpha fetoprotein (AFP) 15, prostate specific antigen (PSA) 16 and carcinoembryonic antigen (CEA) 17, have been used as biomarkers for clinical diagnosis." (PMID 34976172, 2022). "Next, depending on the HBV-positive HCC in the TCGA cohort, we further evaluated the correlation of identified TRIM genes with multiple clinical factors, including Age, fibrosis, gender, AFP levels, neoplasm histologic grade, and vascular invasion." (PMID 35873464, 2022). "In this retrospective study, we showed that AFP and CA19-9, as single tumor markers, are associated with the OS and RFS of HCC patients after radical hepatectomy, consistent with the results of previous studies." (PMID 36258212, 2022). "Further, we studied the prognostic significance of the SNRPA protein expression in early-stage (I+II), low tumor grade (grade I+II), low AFP level (≤400 ng/ml), tumor size ≤ 5cm, Child-Pugh class A, and median/high differentiation subgroups." (PMID 35860579, 2022). "The most common serological tumor marker is α-fetoprotein (AFP), although its sensitivity is around 60%, hardly appropriate for patients’ screening." (PMID 35158892, 2022). "In comparison, the cancer of the liver Italian program (CLIP) scoring system incorporates the CP score along with several tumor criteria (tumor morphology, AFP, and portal invasion)." (PMID 35200757, 2022).
tumor (continued). "The multivariable analysis identified six significant parameters for inclusion in the preoperative Cox model: tumor number, infiltrative appearance, corona enhancement, AFP level > 400 ng/mL, AST level > 40 IU/L, and male sex." (PMID 35554652, 2022). "The multivariate analysis showed age, AFP level, bilirubin level, tumor size, vascular invasion, and previous TACE to be independent predictors of worse prognosis in the case of multinodular HCC." (PMID 36497478, 2022). "Accordingly, it has been clearly shown that AFP provides prognostic information beyond tumor size and number." (PMID 35529597, 2022). "≥76% decrease in AFP change and ≥30% decrease in tumor size of the viable target lesions, taking as reference the baseline target lesions." (PMID 35686094, 2022). "The results showed that there was a significant correlation between the optimal signature and multiple clinical features, including BCLC stage (p=0.011), tumor thrombus (p=0.001), AFP level (p=0.022), TNM stage (p<0.001), and histologic grade (p<0.001)." (PMID 35191375, 2022). "Other factors, such as the BCLC stage, extrahepatic spread, baseline tumor marker (AFP/DCP) levels, ALBI grade, and FIB-4 index should be considered in the management of patients with HCV-related HCC." (PMID 36230773, 2022). "When it is expressed by HCC tumor cells, which is about 70% of the time, alpha-fetoprotein (AFP) is an excellent biomarker for monitoring HCC progression, recurrence, and response to therapy; it is an effective prognosticator of HCC behavior." (PMID 35565184, 2022). "In the training cohort, univariate Cox regression analysis suggested that sex, marriage, year of diagnosis, race, histological tumor grade, T stage, surgery, chemotherapy, AFP, and tumor size were correlated with prognosis." (PMID 35296046, 2022). "Univariate analysis of OS identified nine pretreatment variables as prognostic factors: CTC-NLR, CTC, NLR, AFP, tumor size, tumor number, BCLC stage, PVTT, and MVI." (PMID 35880030, 2022). "AFP-derived peptide-loaded DC vaccines enhance AFP-specific anti-tumor immune response by encouraging CD8 T cell response and NK cell activation, and lowering Tregs." (PMID 36613878, 2022). "Results revealed that inflammatory score (OR = 2.14, 95% CI: 1.63–2.88, p < 0.001), AFP (OR = 2.02, 95% CI: 1.46–2.82, p < 0.001), and tumor size (OR = 2.37, 95% CI: 1.70–3.30, p < 0.001) were independent factors for MVI." (PMID 35310437, 2022). "Maximum tumor size, portal vein invasion, TNM stage, and AFP were strongly associated with overall survival in both groups." (PMID 35729607, 2022). "Univariate analysis identified the following as significant factors predicting unfavorable OS: relative tumor volume in the liver ≥ 50% (p = 0.013), AFP ≥ 400 ng/mL (p = 0.048), and SD as the first-time response of tumor in the MVI (p = 0.002)." (PMID 35655156, 2022). "Our investigation also showed that EXO1 expression levels in the HCC tissues significantly correlated with the AFP levels, overall survival, disease-specific survival, clinical stages, and the tumor status." (PMID 35769911, 2022). "In HCC patients, elevated serum AFP level is positively correlated with poor differentiation, microvascular invasion and tumor recurrence, which is consistent with the biological behavior of CK19-positive HCCs with high aggression." (PMID 36741705, 2022). "Tumor size (P < 0.001), tumor thrombus (P = 0.005), preoperative AFP (P < 0.001) and BCLC stage (P = 0.014 and < 0.001 for B stage and C stage, respectively) were statistically associated with OS in the CHCC cohort." (PMID 35193513, 2022). "We also found that the TRGs-related signature was associated with tumor size, HBV status, AFP level, ALT level, and tumor grade." (PMID 36341373, 2022). "Tumour markers (alpha-fetoprotein, beta-human chorionic gonadotropin) and hormone levels (testosterone) contribute to the differential diagnosis and management of testicular masses in boys." (PMID 35906668, 2022).
tumor (continued). "Futhermore, our results shown that there had no significantly correlation between mutations in exoDNA and other clinicopathological features such as Satellite nodules, tumor number, and AFP." (PMID 35921289, 2022). "The current study demonstrates acceptable post-transplant survival with more liberal expansion of cutoffs on tumor size and number with incorporation of AFP in the selection protocol." (PMID 34117916, 2022). "Although not as effective as BCLC, we did find that MAP3K13 and MAP3K15 were better than AFP and tumor size in predicting prognosis." (PMID 35311629, 2022). "POGK was significantly upregulated in HCC and correlated with tumor status (p = 0.036), race (p = 0.025), weight (p = 0.002), body mass index (p = 0.033), histologic grade (p < 0.001), and alpha-fetoprotein (p < 0.001)." (PMID 36421335, 2022). "Most oncological factors (AFP, explant tumor characteristics, tumor status by radiologic or pathologic assessment, etc.)were not significantly different between the MELD < 20 and MELD ≥ 20 groups." (PMID 35735419, 2022). "AFP levels are a reliable tumor marker in 70%–80% of patients and has been shown to correlate with tumor size." (PMID 36507125, 2022). "Median tumour marker levels were 35.5 ng/mL for alpha fetoprotein (AFP) and 528 mAU/mL for des-gamma-carboxy prothrombin." (PMID 35041693, 2022). "An MVI prediction model incorporating inflammatory score, AFP, and tumor size sifted by logistic regression was eventually constructed." (PMID 35310437, 2022). "Six DEGs were highly expressed in HCC tissues and were significantly associated with the T stage, pathological stage, histological grade, AFP, tumor status, and PT." (PMID 36685860, 2022). "This enabled the analysis of the tumor biomarker alpha-fetoprotein (AFP) in less than 20 min with a LOD as low as 0.07 fM/L, while the quantitative analysis of cocaine was at a LOD of 0.34 μmol/L." (PMID 36290480, 2022). "Serum tumor markers, the “onco”-fetoproteins (AFP and β-hCG), are helpful in the diagnosis and monitoring of GCTs, as well as in the detection of residual or progressive disease." (PMID 35204369, 2022). "The serum tumor marker alpha-fetoprotein (AFP) and carcinoembryonic antigen (CEA) were slightly elevated in two patients (2/20, 10%) and 6 patients (6/20, 30%), respectively." (PMID 35295996, 2022). "Expression levels of IFN-γ receptor on HCC tissues was also negatively correlated with tumour size, serum AFP levels and the occurrence of intrahepatic and extrahepatic metastasis." (PMID 35919490, 2022). "In recent years, models for predicting the recurrence rate of HCC after LT with more accuracy, using various parameters including tumor size, number, and AFP etc., have been reported." (PMID 35053558, 2022). "According to the study, the six up-regulated hub genes were significantly correlated with T stage, pathologic stage, histological grade, AFP, tumor status, and PT." (PMID 36685860, 2022). "An albumin level of <36 g dL−1, AFP levels of >400 ng mL−1, bilirubin levels of >17 μmol L−1, and a maximum tumor diameter of >7 cm are each given 1 point in this scoring system." (PMID 35884412, 2022). "The initial tumor marker levels were AFP (1.3, 2.5, and 147 ng/mL) and PIVKA-II (59, 90, and 1076 mAU/mL)." (PMID 35085305, 2022). "Intrahepatic tumor volume (<50% vs. ≥50%: HR 16.7; 95% CI, 1.71–163; p = .016) and α‐fetoprotein (AFP) (<400 vs. ≥400: HR 3.38; 95% CI 0.84–19.7; p = .031) remained significant factors independently associated with OS." (PMID 35302279, 2022). "Clinically, the common tumour markers of malignant gastrointestinal tumours mainly include embryonic antigens (e.g., AFP and CEA), glycoprotein antigens (e.g., CA-199, CA-125, CA15-3, CA72-4, CA-242, and CA-50) and protein antigens (CyFRA21-1 and Her 2)." (PMID 36109734, 2022).
tumor (continued). "With increasing attention to MVI, serum markers (i.e., AFP) and imaging features as non-invasive examinations before surgery, such as internal arteries and tumor margin, have been used to predict MVI." (PMID 36439486, 2022). "BCLC stage, BMI (kg/m2), tumor size, AFP >= 200 (ug/L), Hepatectomy before TACE, metformin use, and treatment after TACE were associated with OS in the univariate analysis (P<0.1)." (PMID 36187118, 2022). "Early recurrence, the presence of liver recurrence and high AFP level were factors potentially related to tumour biology." (PMID 35956006, 2022). "The results of tumor marker evaluation (AFP—alpha-fetaprotein, β-hCG—beta subunit of human chorionic gonadotropin (CA125—cancer antigen 125, LDH—lactate dehydrogenase) were available for 446 girls (74.96%); however, not all of them were tested in each case." (PMID 35323325, 2022). "AFP serves as a surrogate marker for tumor differentiation as well as vascular invasion and high-level AFP was reported to be linked to HCC recurrence." (PMID 35686100, 2022). "The Metroticket 2.0 is an example of integrated model based on tumor size, tumor number, and AFP level to determine the survival outcomes from HCC-related factors after liver transplantation, useful to refine selection criteria for LT for HCC." (PMID 36497478, 2022). "In this study, a nomogram, based on the large sample size data, was built on the preoperative available data of inflammatory score, AFP, and tumor size." (PMID 35310437, 2022). "The results showed that TCERG1 overexpression was significantly correlated with clinical status, T stage, pathologic stage, histologic grade, tumor status, age, weight, and AFP (ng/ml) (*p < 0.05, **p < 0.01, ***p < 0.001)." (PMID 36299588, 2022). "Serum tumor makers (AFP, β-hCG, LDH, CA 125, estradiol or testosterone) were elevated in 17 cases, including 13 of the 18 patients with malignant tumors and four of the 35 patients with benign tumors." (PMID 35204369, 2022). "The serum biomarkers, CA-153, CA-199, CA-125, CEA, AFP, and CA-724 are tumor markers and have clear predictive significance for a variety of tumors." (PMID 36199582, 2022). "Repeat examinations under anesthesia were usually performed to evaluate tumor response after AFP levels returned to normal levels." (PMID 36452350, 2022). "AFP has been shown to complement other prognostic markers such as the degree of tumor differentiation and microvascular spread on histopathologic examination." (PMID 35227234, 2022). "To evaluate the underlying value of predictors for early tumor recurrence, we analyzed clinical factors consisting of the tumor size, tumor number, tumor grade, BCLC staging, serum AFP level, ctDNA detection status, and tumor mutation profile." (PMID 34543520, 2022). "Since AFP level is related to the tumor or patient characteristics, interpretation should be performed with caution." (PMID 35804984, 2022). "Age, AJCC stages, pathological grade, tumor size, number, AFP, surgery, radiation and chemotherapy were significantly identified in univariate COX regression analysis (P<0.05)." (PMID 36185206, 2022). "They found that, regardless of HCC etiology, the plasma levels of Ang-2, associated with other prognostic factors such as tumor stage, invasiveness and liver function, were better prognostic marker of OS and PFS compared to AFP, VEGF and Ang-1." (PMID 36230569, 2022). "This work included altogether 216 patients with complete data, such as age, sex, tumor grade, T-stage, clinical stage, albumin level, platelet level, AFP level, and vascular invasion from the TCGA-HCC cohort." (PMID 36267406, 2022). "The detection results of serum tumour markers AFP, CEA, CA153, CA125 and CA199 in group A were significantly higher than those in group B (P < 0.05)." (PMID 36755860, 2022). "The Pearson test was performed with the H-score of c-Met in GC tissues and serum tumor markers (AFP, CEA, CA199, CA153, CA125, and CA50) related to the digestive system." (PMID 35710379, 2022).
tumor (continued). "Then, we constructed and validated an MVI prediction model for HCC patients based on preoperative AFP, tumor diameter, and TNM stage, which presented superior predictive efficacy and strong clinical practicability." (PMID 36180867, 2022). "According to current studies, prediction models including serum AFP can enhance the predicting recurrence of tumor after liver transplantation." (PMID 35784933, 2022). "Although the performance of VOCs observed in our study was not better than ultrasound for HCC detection, its sensitivity was greater than the AFP, the main serum tumor marker used in clinical practice." (PMID 35351916, 2022). "In our univariate analysis, patients’ age, smoking status, WBC count, CEA level, AFP level, tumor being malignant or benign, tumor stage T4, lymph node stage N1, and specific tumor types showed a strong association with LIT." (PMID 35978826, 2022). "It is reported that, tumor‐related factors were risk factor for recurrence of HCC patients after curative treatment, such as AFP, tumor size, tumor number, pathological type, etc.." (PMID 36212462, 2022). "The other factors correlated with the OS were tumor size (P < .001), vascular invasion (P = .019), AFP level (P < .001), BCLC stage (P < .001) and TACE times (P = .009)." (PMID 36595771, 2022). "The multivariate analysis revealed that GNRI < 98 (P = .036), tumor size ≥ 5cm (P < .001), tumor number ≥ 2 (P = .037), AFP level ≥ 400 (P < .001) and TACE times < 3 (P = .004) were independent predictors of a poor OS." (PMID 36595771, 2022). "Marital status, α-fetoprotein (AFP), vascular infiltration, tumor size, number of lesions, and grade were independent prognostic factors affecting the 5-year survival rate of HCC patients." (PMID 36451200, 2022). "In tumor size ≤ 5cm, AFP ≤400 ng/ml subgroups, high SNRPA protein expression correlated with poor OS, but not correlated with RFS." (PMID 35860579, 2022). "Routine examination of tumor markers showed 1.6 ng/mL alpha-fetoprotein, 1.2 ng/mL carcinoembryonic antigen, and 65.8 ng/mL ferritin." (PMID 35928973, 2022). "The present study showed the efficacy of crocin and (sorafenib/crocin) treatments in reducing PIVKA-II and AFP levels indicating the anti-tumor activity of both formulations." (PMID 36139719, 2022). "From the results of multivariate analysis, it was found that a larger tumor size, poorer histological differentiation, regional lymph node metastasis, and elevated AFP levels were significantly correlated with distant metastasis risk in small HCC." (PMID 36127436, 2022). "MBD3 expression was significantly correlated with preoperative AFP level (P < 0.001), vascular invasion (P = 0.013), tumour capsule (P = 0.013), Edmondson grade (P = 0.005) and TNM-stage (P = 0.001)." (PMID 35501390, 2022). "Specifically, individuals with high IL-25 levels exhibited higher AFP levels, greater viral loads (≥2,000 IU/ml), and larger tumor sizes (all p < 0.05), indicating that higher IL-25 levels are associated with more advanced HCC." (PMID 36119529, 2022). "The examination of tumor markers showed that levels of alpha-fetoprotein, carcinoembryonic antigen, carbohydrate antigen 19-9 and carbohydrate antigen 12-5 returned to normal, the metastases disappeared, and no new metastases were found." (PMID 36466840, 2022). "A Korean group created a revised scoring system based on tumor size, tumor number and pretransplant AFP levels (< or =20, 20.1 to 200, 200.1 to 1000, >1000 ng/mL), allowing an expansion for candidate selection without adverse outcomes." (PMID 35002508, 2022). "AYA patients had a higher preoperative AFP level and more unfavorable pathological characteristics including tumor size, microvascular invasion, portal vein invasion, and hepatic capsule invasion." (PMID 35729607, 2022).